MPO (myeloperoxidase)
Diseases named in the same sentence as MPO in open-access papers (continued):
Sharing a sentence is not in itself a finding about the gene and the disease.
ulcer (68 papers, 2011 to 2026). "First, measuring secretory protein levels in wound exudate or tissue could aid risk stratification: persistent elevation of MPO may herald an ulcer mired in an inflammatory state, whereas low TREM2 might indicate failure to transition to repair." (PMID 41465092, 2025). "In four mouse ulcer models, pharmacological analysis of the ethanol extract of C. flammula revealed a dose-dependent gastro-protective capability associated with a significant reduction in proton pump and myeloperoxidase activity." (PMID 38474670, 2024). "Given the decrease in MPO activity in rats treated with LS, the subsequent measurement evaluated whether the reduction in neutrophil migration caused this reduction to the ulcer site or by direct inhibition of the MPO enzyme." (PMID 35463093, 2022). "An increased MPO level can promote the proliferation and activation of inflammatory effector cells, and effector cells more easily penetrate endothelial barriers to reach local inflammatory tissues and cause inflammation in the colon and the formation of ulcers." (PMID 34659440, 2021). "Neutrophils also release myeloperoxidase, elastase, and other enzymes that contribute to mucosal injury, potentially leading to erosions and ulcers." (PMID 41228452, 2025). "In parallel with the histopathological findings, treatment with NPW suppressed ulcer-induced increases in myeloperoxidase activity and malondialdehyde level and replenished glutathione level." (PMID 38227096, 2024). "In this study, ethanol-induced gastric injury significantly increased MDA levels and MPO activity in the ulcer group, and KO or FO supplementation to the ulcer groups failed to significantly reduce lipid peroxidation occurrence." (PMID 39458422, 2024). "Similar to that observed in omeprazole-treated rats, treatment with NPW suppressed ulcer-induced increases in MPO activity and MDA level (p < 0.05) and replenished the antioxidant GSH level (p < 0.05)." (PMID 38227096, 2024). "The administration of 2f, 2c and 5-ASA, decreased the ulcers presence, inhibited MPO peroxidation activity and MPO presence (as determined by immunofluorescence), and increased GSH and reduced MDA content." (PMID 39268608, 2024). "In order to qualitatively evaluate the immune cell infiltrates in PALA-treated mouse ulcers, skin tissue was probed using immunofluorescence staining with MPO, NE, F4/80, and CD3 to visualize neutrophils, macrophages, and T cells, respectively." (PMID 37475852, 2023). "We performed immunofluorescence staining of iNOS+ and MPO+ to evaluate the infiltration of inflammatory cells in the ulcer site." (PMID 38001112, 2023). "The gastric MPO was discovered to surge by 250.0% in the ulcer control group referred to the normal control group, showing that there was neutrophil infiltration in the lesion." (PMID 35938492, 2022). "Pre-treatment with ZJP (1, 2, and 4 g/kg) also led to a dose-dependent reduction in the gastric MPO level compared with the ulcer model group." (PMID 35938492, 2022). "In this study, pre-treatment with ZJP (1, 2, and 4 g/kg) led to a dose-dependent decrease in the contents of TNF-α, IL-6 and MPO compared with the ulcer model group." (PMID 35938492, 2022). "Pretreatment with naringenin before ethanol induction suppressed the release of MPO compared to the ulcer control group, who received the vehicle alone." (PMID 34769415, 2021). "Aiming to evaluate the inflammatory process triggered by GS, CS, PS, and Sulf, we measured the production of MPO from ulcer lesions recovered from the animal groups treated with these formulations." (PMID 34827281, 2021). "As expected, both ethanol- and piroxicam-induced ulcer groups showed a high concentration of MPO in the rat stomach, while the AETo groups (30 and 300 mg/kg) decreased the activity of this enzyme, indicating a decrease in neutrophil recruitment." (PMID 34970327, 2021).
ulcer (continued). "In the ethanol-induced ulcer model, the pretreatment with AETo (300 mg/kg) reduced the MPO activity by 66.2%, compared to the vehicle group." (PMID 34970327, 2021). "The main source of ROS in ethanol-damaged gastric tissue is infiltration of activated neutrophils, which MPO is a crucial indicator of neutrophil infiltration in ulcer-induced injuries." (PMID 33324227, 2020). "GMP treatment strongly decreased the number of these inflammatory cells and the MPO activity, and prevented the development of ulcers by indomethacin in the small intestine." (PMID 32443501, 2020). "For the DSS group (Figure 2B2), at 7 days after the termination of DSS administration, the colonic epithelium and the glands disappeared, and the ulcer was locally replaced by scars and massive accumulative MPO+ neutrophils were observed in the scars." (PMID 33519783, 2020). "The stimulated MPO activity is another indication of the degree of ulceration and was found to be enhanced in all the ulcer models studied." (PMID 31194753, 2019). "Nevertheless, the up-regulated activity of myeloperoxidase and tissue content of superoxide anions in the peri-ulcer tissue of diabetic rats was mitigated following Ex4 treatment." (PMID 29095895, 2017). "Systemic administration of Ex4 not only suppressed the cellular infiltration in the peri-ulcer tissue, but also attenuated the tissue levels of myeloperoxidase in diabetic animals." (PMID 29095895, 2017). "In diabetic rats, infiltration of polymorphonuclear leukocytes (PMN) was markedly increased and the expression of myeloperoxidase was enhanced in the ulcer area." (PMID 29095895, 2017). "There was a significant increase in the gastric mucosa MPO activity (170%) in the ulcer control group as compared to the SHAM group (P = 0.007)." (PMID 28250794, 2017). "We found that peritoneal injection of sodium nitroprusside (SNP), a NO donor, decreased the ulcer area, inflammatory cell infiltration and MPO degree in acetic acid-induced gastric ulcer in rats." (PMID 28522805, 2017). "In the current study MPO activity was substantially augmented in the ethanol-induced ulcer control group, confirming neutrophil infiltration in gastric mucosa." (PMID 28587230, 2017). "Luzindole, a MT receptor antagonist, did not inhibit the anti-inflammatory effect of melatonin (macroscopic score 1.12 ± 0.22, ulcer score 0.50 ± 0.16); however, luzindole increased MPO activity (7.57 ± 1.05)." (PMID 26899972, 2016). "Conversely, immunoneutralization of HMGB1 or inhibiting the release of HMGB1 promotes ulcer healing while reducing TNFα expression and MPO activity." (PMID 24244627, 2013). "mRNA expression and MPO activity were evaluated on day 6, and the ulcer index was evaluated on day 9, according to the time course study." (PMID 24244627, 2013). "In contrast, administration of anti-HMGB1 antibody promoted ulcer healing and reduced MPO activity and TNFα expression." (PMID 24244627, 2013). "The gastro-cytoprotective effect of the root bark extract was also accompanied by inhibition of ethanol-induced increase in MPO from 9.20 ± 0.26 μmol/min/mg tissue in the ulcer control to 3.27 ± 0.10 μmol/min/mg tissue in CS-1000." (PMID 23228052, 2012). "TNBS administration led to ulcers in the rectum, increased rectal MPO activity, and up-regulated TNF-α levels." (PMID 21853095, 2011). "A pick dose of 60 mg/kg eAE induced ulcer healing even at the third day of treatment, evidenced by reduced UI and MPO activity in a dose-dependent manner, thereafter with the increase of dose the healing effect gradually decline." (PMID 21076542, 2011). "Similarly, C. sappan extract administration in rats decreased MPO levels, suggesting its potential as a gastroprotective agent in ulcer treatment." (PMID 40990731, 2025). "Additionally, the administration of L-arginine reduced myeloperoxidase activity and accelerated the healing of ulcers." (PMID 41259392, 2025).
ulcer (continued). "In subsequent analyses, we compared gene expression between DFU and non-ulcer samples within each annotated cell type and found that the difference in MPO and LYZ expression between DFU and control was most pronounced in keratinocyte clusters, whereas changes in other cell types were less marked." (PMID 41465092, 2025). "Indeed, our results confirmed the increase in MPO activity at the ulcers site of the ulcerated group treated with the vehicle." (PMID 35463093, 2022). "The degree of ulcer damage, ulcer area, wet weight of intestine and MPO activity were measured." (PMID 32600331, 2020). "On the other hand, ellagic acid exerts antiulcer activity via the: i) inhibition of gastric H+, K + −ATPase, ii) inhibition of acid secretion, and iii) attenuation of lipid peroxidation in the gastric mucosa and myeloperoxidase in the intestinal mucosa of ethanol-induced ulcer model." (PMID 29121900, 2017). "MPO is a crucial indicator of neutrophil infiltration in ulcer-induced injuries." (PMID 28587230, 2017). "In addition, evidence suggests that neutrophils accumulate around active ulcers in UC and that chemokine (IL-8) signals result in neutrophil degranulation followed by the release of myeloperoxidase (MPO) that mediates oxidative stress to produce cytotoxic reactive oxygen species." (PMID 38633005, 2023). "Ulcer area, mucin content, and biochemical indicators (GSH, SOD, CAT, GST, MPO, MDA) were evaluated." (PMID 42043715, 2026). "The results of the experiment showed that KO administration at 500 mg/kg inhibited ulcer formation and decreased tissue MDA levels and myeloperoxidase (MPO) activity." (PMID 40806489, 2025). "While KO, FO, and ASX supplementation decreased chemiluminescence levels in the ulcer group, only ASX supplementation decreased MDA levels and MPO activity." (PMID 39458422, 2024). "In omeprazole-treated ulcer group, as compared to saline-treated rats with ulcer, the gastric levels of MDA, and MPO activity were reduced and gastric GSH content was significantly elevated (p < 0.05)." (PMID 38227096, 2024). "This is evidenced by the decreased tissue MDA and MPO values and increased GSH levels in the ASX-treated ulcer-induced group." (PMID 39458422, 2024). "Meanwhile, AR can prevent the damage of gastric mucosa induced by indomethacin and promote ulcer healing through reducing TNF-α, IL-1β, and MPO, and increasing the PGE2 in the gastric tissue." (PMID 37109624, 2023). "In rats with ethanol-induced ulcers, piperine decreased the ulcer area, increased SOD, CAT and GSH-Px activities, and reduced MDA, ROS and MPO levels." (PMID 36432431, 2022). "Piperine significantly increased SOD, CAT and GSH-Px activities, but decreased the ulcer area, MDA, ROS and MPO levels in the gastric tissues of rats." (PMID 36432431, 2022). "Treatment with NADA and AM630 protected gastric tissues against ulcers as demonstrated by a decrease in the contents of MDA, TNF-α, MPO, and IL-1β along with an increase in the content of PON-1 activity and GSH in the stomach tissues." (PMID 35083004, 2021). "In ulcer-induced group the anti oxidant enzymes SOD, CAT, GPX, LPO and MPO were decreased when compared with control group." (PMID 34393417, 2021). "Pretreatment with genistein significantly improved ulcer indexes and increased the level of NO, PGE2 and SOD activity and significantly decreased MDA, levels of TNF-α and MPO activity, and expression of MMP-9 was negatively regulated." (PMID 33233494, 2020). "In agreement to this observation, neutrophils express MPO, neutrophil elastase and MMP9 at the edge of ulcers and necrotic areas in lesions of patients with mucosal leishmaniasis, indicating their potential involvement in lesion ulceration." (PMID 28591228, 2017).
ulcer (continued). "The inhibition of MPO (a marker of neutrophils infiltration) and TNF-α levels by RGal treatment suggests a reduction of neutrophils migration at the ulcer site and consequently promotes an improvement of the gastric inflammatory process induced by acetic acid." (PMID 24416280, 2014). "Ulceration induced with ethanol was significantly inhibited with MEAL, and the extract also resulted in the reduction of both lipid peroxidation and myeloperoxidase activity." (PMID 23008816, 2012). "MPO activity in hepatic tissues increased in the ethanol-induced ulcer group, but the results were not statistically significant (p > 0.05)." (PMID 39458422, 2024). "However, in ulcer-rat treated with OLE and OLR, a significant decrease in gastric MPO activity (by 47 and 30%, respectively) and an increase in NO rate (by 38 and 33%, respectively)was observed." (PMID 38911236, 2024). "Pretreatment of TRPV1 antagonist did not change the MPO activity in tissues (n = 8, P = 0.48 vs ulcer control group), but abolished the effect of SNP." (PMID 28522805, 2017). "Malondialdehyde (MDA) and myeloperoxidase (MPO) levels were significantly (p < 0.05) elevated (2.63- and 3.59-fold, respectively) and the prostaglandin E2 (PGE2) level was decreased (2.47-fold) in the ethanol-induced ulcer control group." (PMID 28587230, 2017). "AA caused a significant reduction in body weight and induced macroscopic and microscopic ulcers, along with a significant decline of endogenous antioxidants (superoxide dismutase (SOD), catalase, and GSH), with a concomitant increase in MDA level and MPO activity." (PMID 40943092, 2025).
acute coronary syndrome (67 papers, 2008 to 2026). Signs and symptoms related to acute ischemia of the myocardium secondary to coronary artery disease. "Studies have demonstrated that MPO levels are higher in CAD, and elevated circulating levels of MPO in acute coronary syndrome have been shown to be associated with a worse prognosis in those patients." (PMID 37373746, 2023). "This is supported by earlier studies indicating a pathophysiological role of MPO in the context of atrial fibrillation, HF, responsiveness to resynchronization therapy and risk prediction in acute coronary syndromes." (PMID 36670895, 2022). "In a study using MPO to predict the risk for acute coronary syndromes, MPO serum levels are up to ∼600 μg/liter (∼8 nM)." (PMID 35019674, 2022). "Myeloperoxidase has been proposed as a useful risk marker and diagnostic tool in acute coronary syndromes and patients admitted to an emergency room for chest pain, as increased serum levels of MPO are predictors of major adverse cardiac events." (PMID 35175161, 2022). "Elevated levels of MPO are observed in plasma and serum from individuals with acute coronary syndromes or at risk for major adverse cardiac events." (PMID 34331945, 2021). "Other studies have suggested that MPO is a risk factor for predicting mortality after acute coronary syndrome." (PMID 33410147, 2021). "As expected from the selection criteria, average plasma MPO concentration in this cohort was slightly lower than literature reports on higher-risk patients, such as those presenting with acute coronary syndrome (ACS)." (PMID 25666092, 2015). "For example, a previous large study has shown that serum MPO levels are associated with acute coronary syndromes among those who present to emergency departments with acute chest pain." (PMID 23637811, 2013). "Additional studies demonstrated an increased cardiac risk with elevated serum levels of MPO in patients with acute coronary syndromes, and an increased odds ratio for major adverse cardiac events in a cohort of patients presenting with chest pains." (PMID 21188207, 2010). "In conclusion, leukocyte counts and levels of fibrinogen, CRP, myeloperoxidase, and pregnancy associated plasma protein-A were increased in patients with acute coronary syndromes." (PMID 21188207, 2010). "Mitchell and colleagues used a multi-marker approach in low risk subjects and also found that MPO had poor predictive utility for acute coronary syndromes within 45 days." (PMID 23675127, 2009). "Plasma MPO levels have been linked to risk of acute coronary syndrome in several studies." (PMID 29572498, 2018). "Notably, MPO is a potent inducer of oxidative stress via production of hypochlorous acid, and plasma levels of MPO have been positively linked to risk of acute coronary syndromes in humans." (PMID 29572498, 2018). "In addition to its antimicrobial action, MPO also has potent proatherogenic properties and elevated serum levels of MPO have been associated with acute coronary syndromes." (PMID 23637811, 2013). "MPO has been detected in human atherosclerotic lesions and high serum MPO is reported to be a risk factor for early adverse cardiac events in patients with acute coronary syndromes." (PMID 22078494, 2011). "Previous studies suggested that MPO may have utility for risk stratification of ED patients with chest pain and patients with acute coronary syndromes." (PMID 23675127, 2009). "The purpose of this review is to provide an overview of the pathophysiological, analytical, and clinical characteristics of MPO and to summarize the state of art about the possible clinical use of MPO as a marker for diagnosis and risk stratification of patients with acute coronary syndrome (ACS)." (PMID 18382609, 2008). "In line with this, long-term SSRI treatment in patients and animal models showed lower levels of myeloperoxidase and reduced neutrophil degranulation in the pathophysiological setting of the acute coronary syndrome." (PMID 36675065, 2023).